ENSG00000259784 (novel protein)
Gene: Protein-coding gene on chromosome 16 (2,513,965 to 2,527,955, forward strand). Ensembl gene ENSG00000259784.
Genetic constraint (gnomAD): Loss-of-function variants: 9 observed, 10.93 expected, observed/expected ratio (o/e) 0.82, 90% interval 0.5 to 1.43. The synonymous counts are far from expectation, so gnomAD's model fits this gene poorly and the ratio says little. Missense variants: 199 observed, 195.51 expected, observed/expected ratio (o/e) 1.02, 90% interval 0.91 to 1.14. Synonymous variants: 125 observed, 89.84 expected, observed/expected ratio (o/e) 1.39, 90% interval 1.2 to 1.61.